GFAP (glial fibrillary acidic protein)
Description:
GFAP, a class-III intermediate filament, is a cell-specific marker that, during the development of the central nervous system, distinguishes astrocytes from other glial cells.
Synonyms: FLJ45472; ALXDRD
Tractability: PROTAC: its protein half-life has been measured.
Gene: Protein-coding gene on chromosome 17 (44,903,159 to 44,916,937, reverse strand). Ensembl gene ENSG00000131095.
Subcellular location: Cytoplasm
Subcellular location (Human Protein Atlas): Intermediate filaments
Pathways (Reactome):
Autophagy: Chaperone Mediated Autophagy
Signal Transduction: Nuclear signaling by ERBB4
Gene Ontology:
Molecular function: identical protein binding; protein binding; structural constituent of cytoskeleton; integrin binding; kinase binding
Biological process: enteric nervous system development; intermediate filament organization; neural crest cell migration; regulation of chaperone-mediated autophagy; regulation of protein-containing complex assembly; positive regulation of glial cell proliferation; response to ethanol
Cellular component: cytoplasm; intermediate filament cytoskeleton; cytosol; intermediate filament; lysosome; astrocyte end-foot; astrocyte projection; cell body; cytoplasmic side of lysosomal membrane; cytoskeleton; glial cell projection; membrane
Genetic constraint (gnomAD): Loss-of-function variants: 34 observed, 45.68 expected, observed/expected ratio (o/e) 0.74, 90% interval 0.56 to 0.99. The upper end of that interval is the gene's LOEUF score, 0.99, which puts it in group 4 of 6, group 1 being the genes least tolerant of losing a copy. Missense variants: 452 observed, 576.92 expected, observed/expected ratio (o/e) 0.78, 90% interval 0.73 to 0.85. Synonymous variants: 217 observed, 236.78 expected, observed/expected ratio (o/e) 0.92, 90% interval 0.82 to 1.03.
Gene-disease validity (ClinGen):
ClinGen rates the evidence that GFAP causes each of these diseases.
Alexander disease (autosomal dominant): Definitive. Alexander disease (AxD) is a rare neurodegenerative disorder of the astrocytes comprised of two clinical forms: AxD Type I and Type II manifesting with various degrees of macrocephaly, spasticity, ataxia and seizures and leading to psychomotor regression and death.
Homologues: Orthologues: chimpanzee GFAP (97% identical), dog GFAP (93% identical), pig GFAP (93% identical), rat Gfap (91% identical), macaque GFAP (91% identical), mouse Gfap (90% identical), guinea pig GFAP (89% identical), rabbit GFAP (87% identical), zebrafish gfap (67% identical). Paralogues in human: VIM (57% identical), DES (56% identical), PRPH (54% identical), INA (43% identical), NEFM (42% identical), NEFL (41% identical), KRT8 (34% identical), KRT75 (33% identical), KRT6C (32% identical), KRT5 (32% identical), KRT6B (32% identical), KRT85 (31% identical), and 56 more.
Diseases named in the same sentence as GFAP in open-access papers:
GFAP is named in the same sentence as 677 diseases in open-access papers, as found by Europe PMC text mining. Sharing a sentence is not in itself a finding about the gene and the disease. The quoted sentences say what the papers report.
glioma (436 papers, 1984 to 2026). A benign or malignant brain and spinal cord tumor that arises from glial cells (astrocytes, oligodendrocytes, ependymal cells). "It has been reported that astrocytes surrounding gliomas upregulate GFAP expression and that tumor-associated astrocytes and microglia acquire an anti-inflammatory/pro-tumoral state." (PMID 39921723, 2025). "Recently, serum GFAP (sGFAP) was shown to be closely linked with glioma, but additional studies are necessary to fully explore the potential of sGFAP as a rapid tool for the diagnosis and follow-up of glioma and definite acting mechanism of GFAP in GBM." (PMID 38216970, 2024). "GFAP, one of the major markers for glioma-associated astrocytes, is significantly upregulated in the co-cultures, indicating the presence of this phenotype." (PMID 38317968, 2024). "Remarkably, GFAP a well-known marker for Glioma-associated astrocytes (GAAs), strongly upregulated in our 3D GBM spheroids by 575-fold (bi-culture with GBM cells) and 337-fold (tri-culture), confirming the successful differentiation towards a GAA-like state." (PMID 38317968, 2024). "Firstly, serum GFAP levels were studied as potentially informative for the prognostic and diagnostic evaluation of some neoplastic forms, such as gliomas." (PMID 36769380, 2023). "Modifications in the structure and assembly of the GFAP network have been linked to a more malignant glioma phenotype." (PMID 37886397, 2023). "At the same time, we collected the immunohistochemical and genetic detection results of glioma patient samples, including Vimentin, S-100, GFAP, SYN, EMA, CD34, Ki67, IDH mutation, MEMG methylation and 1p/19q lost and other information." (PMID 36831736, 2023). "High-grade gliomas are associated with alternative splicing in GFAP expression, as GFAPα is downregulated while GFAPδ has an increased dominance in these tumors." (PMID 35372061, 2022). "DLK1 gene expression was previously reported to be upregulated in isolated GFAP+ tumor-associated astrocytes of high-grade glioma compared to those of lower-grade tumors, further confirming DLK1 expression in astrocytes in this model system." (PMID 33142235, 2020). "On the other hand, decrease in GFAP expression was associated with depression and growth of gliomas." (PMID 30526520, 2018). "Previous studies have reported association of increased GFAP levels and hypertrophic changes with susceptibility to toxic insult in C6 rat glioma cells." (PMID 24987671, 2014). "In one of the mouse models developed to study glioma origin, c-myc expression under the GFAP promoter in developing astroglia predisposes to malignant gliomas." (PMID 23888189, 2012). "Our results suggest that non-invasive, quantitative bioluminescent imaging using GFAP-luc reporter animal is a useful tool to monitor temporal-spatial kinetics of host-mediated astrogliosis that is associated with glioma and metastatic brain tumor growth." (PMID 21247490, 2011). "Such gliomas express glial fibrillary acidic protein (GFAP) and are associated with high proliferation potential." (PMID 19874583, 2009). "Changes in GFAP alternative splicing are linked to glioma malignancy." (PMID 37509607, 2023). "Loss of GFAP expression is typical in high grade glial tumors." (PMID 35745855, 2022). "Moreover, the exploration of expression data shows that GFAP is highly expressed in low-grade glioma (LGG) patients, and this high expression is associated with a lower survival rate." (PMID 36081550, 2022). "Interestingly, we found that a subset of TAMs also express genes encoding the markers of glioma cells, such as GFAP, DLL3, OLIG1 and SOX4." (PMID 34805184, 2021).
glioma (continued). "Notably, taxol was suggested to trigger differentiation in some glioma cells and in one study associated with an increase in GFAP expression." (PMID 31003495, 2019). "Induction of permeability in temozolomide-treated glioma model rats was associated with reduction in tumor volume, increased GFAP expression, and reduced Ki-67 expression, suggesting that BBB permeabilization with this experimental technique can improve delivery of temozolomide to the brain." (PMID 30534564, 2018). "The current clinical diagnostic of glioma is based mainly on imaging diagnostic and anatomopathological findings in biopsy pieces, including markers such as GFAP or Ki-67 to indicate proliferative activity, which, for this type of cerebral tumor, is especially high." (PMID 25298751, 2014). "Only one of the prior case reports associating gliomas with cysticercosis in the English literature has been reported on any immunostain evaluation of the tumor; in that case it was only a positive glial fibrillary acidic protein immunostain in an anaplastic astrocytoma." (PMID 24151568, 2013). "The data showed that glioma-specific radioiodine intake was caused by transfection with the hNIS gene under the control of the GFAP promoter, but the GFAP promoter may also have been activated by normal astrocytes in the CNS." (PMID 23420532, 2013). "In addition, the primary cells expressed good glial acidic protein (GFAP), the hallmark of gliomas." (PMID 31094020, 2019). "Interestingly, one study has isolated GFAP expressing cells from blood of grade IV astrocytoma patients and showed that they contain astrocytoma specific mutations, indicating that GFAP positive glioma cells can leave the tumor and enter the bloodstream." (PMID 30667110, 2019). "With the fiber-swap mutations and the optimized glial fibrillary acidic protein promoter, the mutation truncating the i-leader open reading frame protein constitutes a new addition to our arsenal of validated modules for inclusion in new replicating glioma-targeted adenoviruses." (PMID 21477385, 2011). "For most of these models, histopathological analyses revealed highly proliferative tumors showing features of human high-grade glioma including necrosis, pleomorphic nuclei, and positive staining for glial cell markers (GFAP and/or OLIG2)." (PMID 41381884, 2026). "Taken together, these reciprocal changes in NeuN and GFAP expression suggest that ASPHD1 promotes neuronal-like differentiation in glioma cells." (PMID 41551155, 2025). "Glioma cell secretory products can directly induce GFAP-positive reactive astrocytes, and models of glioma-associated reactive astrocytes have been constructed in multiple studies based on this understanding." (PMID 40243478, 2025). "BBG co-localized with GFAP-positive glioma cells, supporting the conclusion that BBG identifies tumor cells." (PMID 41226489, 2025). "Confirmed via cytology, sEVs from the plasma of glioma patients exhibited enrichment of ephrin type-A receptor 2 (14.7-fold), tenascin C (22.7-fold), and glial fibrillary acidic protein (8.4-fold)." (PMID 41373835, 2025). "Immunocytochemistry demonstrated expression of both GFAP (used as a marker of differentiated glioma cells) and P2X7R with co-expression of these markers demonstrated throughout the cell." (PMID 40956832, 2025). "In this study, we highlighted the astrocytic GFAP staining quality of specific tumor cells, and in one case, an infiltrative glioma-like pattern developed." (PMID 41464145, 2025). "From a methodological perspective, this study establishes the feasibility of the multi-marker detection approach (EGFR+/GFAP+/CD45-) for reliable identification of glioma-derived CTCs." (PMID 40214852, 2025). "Subsequently, to determine the localization of bacteria in glioma tissue, we quantified the cells co-expressing GFAP and LPS, as well as CD68 and LPS, using multicolor immunofluorescence staining on tissue sections." (PMID 39660865, 2025).
glioma (continued). "Statistical analysis revealed a significantly higher abundance of GFAP+LPS+ cells compared to CD68+LPS+ cells in glioma tissues." (PMID 39660865, 2025). "C6 is an established cell line derived from rat glioma that can differentiate into astrocyte-like cells, express glial fibrillary acidic protein (GFAP) under specific conditions and has been used to culture astrocyte models." (PMID 40332055, 2025). "NRG2 is highly expressed in glioma tissues across various grades and modulates the expression of GFAP in glioma cells via the Akt signaling pathway, impacting the prognosis of glioma patients." (PMID 40584443, 2025). "Although BBG also lightly stained some extracellular or stromal material within the glioma (possibly tumor matrix), its predominant localization was within GFAP-positive tumor cells." (PMID 41226489, 2025). "In these subtypes, AC-like glioma cells express some characteristic astrocyte markers, such as S100B, GFAP, SLC1A3, GLAST, and MLC1." (PMID 40243478, 2025). "At the same time, the glioma cells formed in this way all express common astrocyte markers, such as glial fibrillary acidic protein (GFAP)." (PMID 40243478, 2025). "Earlier studies investigating GFAP staining in high-grade glioma cells have revealed diminished GFAP expression in giant cell glioma." (PMID 39821858, 2025). "For GFAP isoform ratios, a change in the GFAPα/GFAPδ ratio has been shown to alter cell‐environment interactions and cell migration in the context of glioma cell invasion (van Asperen, Robe, & Hol, 2022)." (PMID 39289040, 2025). "Although light staining of extracellular or stromal material within the tumor mass was also observed—potentially reflecting binding to matrix components—the predominant localization of BBG was within GFAP-positive glioma cells." (PMID 41226489, 2025). "Astrocytomas express glial fibrillary acidic protein, an intermediate filament found in astrocytes that is routinely used as an aid in classifying a glioma as an astrocytoma." (PMID 38707095, 2024). "Serum GFAP correlates with invasiveness in astrocytomas and high-grade gliomas, compared to lower grade gliomas." (PMID 38879494, 2024). "In our study, gliomas with high GFAP expression exhibited significantly higher uptake of 68Ga-FAPI than GFAP-negative gliomas." (PMID 39629119, 2024). "We selected N-cadherin, a mesenchymal-type marker that is sensitive to 7 in U87 cells in vitro, and glial fibrillary acidic protein (GFAP), which plays an important regulatory role in glioma cell motility, as markers of interest." (PMID 39135794, 2024). "Hematoxylin and eosin (H&E) staining highlights key aspects of human glioma, such as hemorrhage, increased cellularity, nuclear vascular proliferation, and necrosis in the brain tumor tissues of GFAP-Cre; KrasG12D; APCL/+; p53L/L mice (Figure 2Bi–Biii)." (PMID 38473403, 2024). "Concerning gliomas, it is stated that the lower the levels of GFAP are, the higher the WHO grade of the gliomas." (PMID 39062515, 2024). "To further elucidate the biological importance of HEC1, we performed multiplex fluorescent immunofluorescence staining of macrophage marker CD68, CD163, along with glioma cell marker Glial fibrillary acidic protein (GFPA), across different grade of glioma." (PMID 39021287, 2024). "We performed a similar analysis in high-grade glioma tissue from a human patient, staining for GFAP, which in glioma patients marks both astrocytes and glioma cells, and α-SMA, a marker of pericytes, which envelope blood vessels." (PMID 38295184, 2024). "Glial fibrillary acidic protein-mutant gliomas exhibited higher 68Ga-FAPI-46 uptake than wild-type gliomas." (PMID 39629119, 2024). "Our triple staining experiment (vimentin, Iba1, GFAP) of low-grade glioma tissues showed that dExPath can reveal substantially increased colocalization between these cell type markers, with implications for the analysis of cell populations in glioma biology." (PMID 38295184, 2024).
glioma (continued). "As in the previous study, we found that GFAP, as compared to the other three proteins, had the highest discriminatory potential between gliomas and meningiomas." (PMID 38879494, 2024). "Conversely, the examination of the brains of GFAP-Cre; KrasG12D; p53L/L mice reveals a few high-grade glioma characteristics, including heterogeneous lesions, spindle cells, large and elongated nuclei, bipolar processes, and a few giant cells." (PMID 38473403, 2024). "GFAP is a specific glioma marker, and its expression level is positively correlated with tumour grade 32." (PMID 39629119, 2024). "We also demonstrated colocalization of CXCL12 with CD31+ endothelial cells and GFAP+ tumor (glioma) cells, in particular, identifying these cell populations as important sources of CXCL12." (PMID 38806504, 2024). "GFAP mutant gliomas exhibited significantly higher 68Ga-FAPI-46 uptake than wild-type (4.86 vs. 1.35, P = 0.01)." (PMID 39629119, 2024). "Linear regression analysis revealed that the number of CD68‐positive cells was significantly positively correlated with the number of GFAP+PDPN+ cells in glioma, with CD68+CD163+ cells showing a similar association with GFAP+PDPN+ cells." (PMID 38470096, 2024). "GFAP-targeted anti-tumour drugs efficiently inhibit glioma cell proliferation and promote apoptosis." (PMID 39629119, 2024). "GFAP, NEFL, FABP4 and MMP3 are useful for differential diagnosis and prognosis, and are associated with molecular changes in gliomas." (PMID 38879494, 2024). "Future studies are needed to confirm menin’s interaction with GFAP and vimentin in additional glioma cell lines and patient samples, as well as to investigate the effects of menin on glioma cell migration and invasion." (PMID 39336822, 2024). "We also conducted immunofluorescence staining for glial markers GFAP, glioma stem cell markers SOX2, tumor proliferation marker Ki-67 and invasion markers Vimentin." (PMID 37891669, 2023). "Since GFAP is highly expressed in neuroprogenitor and neural stem cells that can give rise to gliomas as well as in gliomas themselves, such mice provided the opportunity to monitor effects of DN-ATF5 on both glioma formation and persistence." (PMID 36831248, 2023). "In conclusion, our results demonstrate that glioma cells are interconnected through GFAP-positive TNTs containing active mitochondria." (PMID 37886397, 2023). "For some cancers, such as glioma, one protein (GFAP) is given a high score with considerably lower scores for the other proteins (<50%), while in other cancers there is a continuum of importance scores, such as AML or colorectal cancer." (PMID 37463882, 2023). "According to another prognostic analysis, GFAP expression and MGMT promoter methylation were linked to the survival prognosis of patients with glioma." (PMID 37090987, 2023). "We confirmed that these cells lines were diffuse high-grade glioma as they were all positive for Olig2 except for J3T-Bg cell lines, and astrocytic type for those positive for GFAP and Vimentine." (PMID 38098992, 2023). "Some statistics show that the positive rate of GFAP in the diagnosis of glioma is approximately 85–95%." (PMID 36831736, 2023). "GFAP is characteristic of astrocyte- and neural stem cell-derived gliomas in CNS tumors and is used to identify malignancies of glial origin, such as astrocytomas and GBM." (PMID 37886397, 2023). "The effect of radiotherapy target area and glial fibrillary acidic protein (GFAP) on the prognosis of high-grade glioma and its mechanism, number ChiCTR2100046667." (PMID 37287919, 2023). "In glioma, IVM showed that GFAP splice variants fine‐tune invasion by modulating migration persistence." (PMID 37261345, 2023).